TNF (tumor necrosis factor)
Diseases named in the same sentence as TNF in open-access papers (continued):
Sharing a sentence is not in itself a finding about the gene and the disease.
cervical carcinoma (continued). "The tumor necrosis factor alpha (TNF-α) cytokine plays an important role in all stages of cervical cancer and has the ability to induce the regression of human tumors." (PMID 16438713, 2006). "Distribution (%) of -308 TNF-α genotypes in women with cervical cancer among different population groups." (PMID 16438713, 2006). "Our findings provide new insights into the anti-cancer potential of DHC and suggest that it may serve as a valuable adjuvant agent to overcome survival signaling and improve the efficacy of TNF-α-based therapeutic strategies in cervical cancer." (PMID 40507823, 2025). "For instance, in cervical cancer, TNF activates the NF-κB signaling pathway, inducing the expression of chemokines such as CXCL1 and CXCL8, which promotes the infiltration of neutrophils and macrophages, thereby facilitating tumor progression and immune evasion." (PMID 40517358, 2025). "Furthermore, cytokine release (TNF-α, IFN-γ, and IL-2), which is a hallmark of T-cell activation upon tumor cell lysis, was also induced by TF-BiTE in cervical cancer cell lines." (PMID 41009508, 2025). "In cervical cancer HeLa cells cultured with fluoride concentrations of 1–50 mg/L for 48 h, there was a strong increase in IL-1β, IL-6, and TNFα levels in the supernatant at the lowest concentration (1 mg/L), followed by a significant decrease at higher concentrations." (PMID 40497976, 2025). "VC can potentially impact cervical cancer through pathways involving TNF-α and p21125, which may interact with the anti-cancer pathway of VD." (PMID 38230221, 2024). "IL-6, TNF-α, and granulocyte-colony-stimulating factor (G-CSF) have been identified as significant contributors to neutrophilia in various malignancies, including anal cancer, cervical cancer, and CRC." (PMID 38041687, 2024). "Moreover, in cervical cancer, miRNA-130a downregulates TNF-α expression while TNF-α decreases the expression of miRNA-130a by activation of NF-κB." (PMID 37736898, 2023). "In addition, to further investigate the effect of TNF-α on the progression of cervical cancer, a C33A subcutaneous xenograft model was established in vivo." (PMID 37124061, 2023). "We found that TNF-α significantly stimulated cervical cancer cells to secrete VEGFC." (PMID 37124061, 2023). "In general, TNF-α could promote cervical cancer tumorigenesis, lymphangiogenesis, and lymphatic metastasis in vivo via activating VEGFC-mediated AKT and ERK pathways." (PMID 37124061, 2023). "In this study, we only determined that TNF-α could inhibit cervical cancer progression by targeting VEGFC-mediated AKT and ERK pathways." (PMID 37124061, 2023). "Moreover, GLPs reduced the expression of pro-inflammatory cytokines, such as IL-1β (interleukin-1β), IL-6 (interleukin-6), and TNF-α (tumor necrosis factor-alpha), in rats with cervical cancer." (PMID 38104078, 2023). "Therefore, this study was the first to explore the effect of TNF-α on the progression of cervical cancer from the perspective of the TME." (PMID 37124061, 2023). "Morphological change of cervical cancer cells—change of cell shape from cobblestone (epithelial) to spindle-like narrow elongated shape (mesenchymal)—has been implicated as a marker of EMT and reported to be induced in cervical cancer cells by treatment with TGF-β as well as TNF-α." (PMID 36766756, 2023). "Nevertheless, the relationship among TNF-α, lymphatic microvessel formation, and tumorigenesis in cervical cancer remains unclear." (PMID 37124061, 2023).
cervical carcinoma (continued). "Our results also demonstrated that the DEGs were inversely correlated with TNF signaling, suggesting that the anti-tumor effects of PKU12 + siRNA treatment may be related to TNF signaling in cervical cancer." (PMID 37350944, 2023). "Collectively, TNF-α could promote tumorigenesis, lymphangiogenesis, and lymphatic metastasis in vitro and in vivo in cervical cancer via activating VEGFC-mediated AKT and ERK pathways." (PMID 37124061, 2023). "Our findings suggest that TNF-α could be apromising target for cervical cancer treatment, as it promote lymphangiogenesis and lymphatic metastasis by upregulating VEGFC." (PMID 37124061, 2023). "Additionally, the CM collected from the TNF-α-treated cervical cancer cells notably promoted the proliferation, migration, and angiogenesis of HLECs; however, these changes were reversed by MAZ51, a VEGFR3 inhibitor." (PMID 37124061, 2023). "Finally, to confirm the effect of TNF-α on cervical cancer tumorigenesis and lymph node metastasis, a C33A subcutaneous xenograft model was established in vivo." (PMID 37124061, 2023). "Further, employing synthetic poly-methyl methacrylate adjuvant with a recombinant E7 DNA vaccine could increase the level of TNF-α and IL-6 in cervical cancer models." (PMID 35752792, 2022). "The pooled analysis showed that XRCC3 RS861539, TNF-α rs1800629, and IL-6 rs1800795 were associated with cervical carcinoma susceptibility, but not MTHFR rs1801133, IL-12B rs3212227 and TLR9 rs352140 polymorphisms." (PMID 34837895, 2021). "There have been publications showing that the TNF-α pathway plays important roles in regulating tumor proliferation, migration, invasion and angiogenesis, and the host-defense peptides caerin 1.1 and 1.9 stimulate TNF-α-dependent apoptotic signals in human cervical cancer (HeLa) cells." (PMID 33948902, 2021). "BCL2A1 was induced by NF-κB signaling after TNF-α treatment in cervical cancer cells." (PMID 34572804, 2021). "In the present study, we investigated the growth-inhibiting activity and apoptosis-inducing effect of [Cu(PMPP-SAL)(EtOH)] on cervical cancer HeLa cells in vitro, as well as its effects on the NF-κB signaling pathway induced by TNF-α, and the MAPK cell signaling pathway." (PMID 33106514, 2020). "In this study, we observed that two cervical cancer cell lines had no significant loss in the cell viabilities after treated with various concentrations of TNF‐α ranging from 0.1 to 50 ng·mL−1 when compared with vehicle‐treated cells." (PMID 29632814, 2018). "In parallel, several cervical carcinoma-derived cell lines have been shown to be resistant to TNF anti-proliferative effect, suggesting that the acquisition of TNF-resistance may constitute an important step in HPV-mediated carcinogenesis." (PMID 29774090, 2018). "Furthermore, G.A enhances tumor necrosis factor (TNF)-α-induced G1 cell cycle arrest by downregulating cyclin D1 and retinoblastoma phosphorylation in the HeLa cervical cancer cell line." (PMID 30210348, 2018). "The Lnc-IL7R-induced decreased expression of TNF-α might be conducive to the progression of cervical cancer." (PMID 29720427, 2018). "We guessed that the TNF‐α‐stimulated expression of miR‐130b might be involved in the resistance of cervical cancer cell to TNF‐α killing." (PMID 29632814, 2018). "These evidences presented that there was a causal relationship between the accumulation in miR‐130b and the reduction in PTEN mRNA or protein level in cervical cancer cell and supported that miR‐130b mediated the TNF‐α‐stimulated inhibition of PTEN gene expression." (PMID 29632814, 2018). "Based on these facts, we considered that the TNF‐α‐promoted expression of miR‐130b in cervical cancer cell might be through the activation of NF‐κB signalling pathway." (PMID 29632814, 2018).
cervical carcinoma (continued). "Considering other SNPs previously reported to be associated with cervical cancer, only at the MHC TNF locus was association observed in the current study; this association is not observed having conditioned on the major HLA protective and risk alleles or amino-acids." (PMID 28806749, 2017). "Furthermore, qRT-PCR and Western blot analysis showed that miR-130a decreased TNF-α mRNA and protein expression levels in cervical cancer cells compared with the control." (PMID 24885472, 2014). "The basic research showed that P2 could suppress the production of nitric oxide in LPS-induced RAW264.7 macrophage cells as well as the secretion of inflammatory cytokines IL-6 and TNF-α in human cervical cancer HeLa cells." (PMID 24683359, 2014). "TNF-α concentrations also tend to be higher in women with cervical carcinoma." (PMID 24683359, 2014). "These experiences motivate us to argue that OA-MNPs with photo-immobilized DOX, FOL, TNF-α plus IFN-γ could remarkably enhance the inhibition to human cervical cancers." (PMID 24845203, 2014). "Numerous studies indicate that TNF-α may influence the fate of HPV-infected cells and suggest that HPV-mediated TNF resistance is a key event in the multistep process leading to cervical cancer." (PMID 23533798, 2013). "The development of cervical cancer is induced by persistent HPV infection, and TNF-α may be involved in the susceptibility to HPV infection and development of cervical cancer by modulating viral replication." (PMID 24015171, 2013). "Since the malignant development of cervical cancer is induced by persistent viral infection, we focus on the TNF gene, which may be involved in the susceptibility to HPV infection and development of cervical cancer." (PMID 23028877, 2012). "Furthermore, cervix carcinoma specimens revealed TNF-α immunoreactivity in peritumoral cells and carcinoma cells." (PMID 18257926, 2008). "In addition, TNF-α has a stimulatory effect on the migration of SW756 cervical carcinoma cells and it induces motility of different epithelial tumor cell lines." (PMID 18257926, 2008). "Since TNF-α was found to be present in the cervix carcinoma tissue it may have the capability to promote the spread of carcinoma cells." (PMID 18257926, 2008). "However, previous in vitro studies indicate that the TNF-α treatment can rather maintain the growth of cervical carcinoma cells, or even stimulate their growth in one study, than cause growth inhibition and cytolysis." (PMID 18257926, 2008). "In addition, the treatment with epidermal growth factor of ME180S cervical carcinoma cell line has been found to protect these TNF-α sensitive cells from TNF-α induced apoptosis." (PMID 18257926, 2008). "The presence of TNF-α positive cells in the cervix carcinoma and control samples." (PMID 18257926, 2008). "In the cervix carcinoma, the malignant cells may resist this endogenous cytolytic action and TNF-α could even enhance carcinoma cell migration." (PMID 18257926, 2008). "First, we asked whether lysosomal cysteine proteases might be involved in apoptosis induced by TNF in the cervical carcinoma cell line HeLa." (PMID 14562034, 2003). "Similarly, a previous study showed that miR-21 upregulates TNF-α mRNA and protein expression levels through an unknown target in HeLa cells in cervical cancer, thereby affecting its proliferation." (PMID 40104397, 2025). "Furthermore, this study showed that TNF-α could stimulate cervical cancer cells to secrete VEGFC, which in turn promoted the proliferation, migration, and angiogenesis of HLECs." (PMID 37124061, 2023). "However, the mechanism through which TNF-α regulates lymphatic metastasis in cervical cancer remains unclear." (PMID 37124061, 2023). "Thus, further study is needed to investigate whether TNF-α could affect the progression of cervical cancer via targeting other pathways, such as AMPK/mTOR or the NF-κB signaling pathway." (PMID 37124061, 2023).
cervical carcinoma (continued). "Furthermore, TNF-αelevated D2-40 and VEGFC protein expressions in tumor tissues, indicating that TNF-α could promote lymphangiogenesis and lymphatic metastasis of cervical cancer in vivo." (PMID 37124061, 2023). "Thus, it indicated the knockdown of WASL might be correlated with biological processes such as glycolysis, TNFα signaling, mTOR signaling, and Wnt/β-catenin signaling, which, in return, might suppress the progress of cervical cancer in clinical settings." (PMID 34222242, 2021). "Hence, in the present study, it was of interest to know about the functional outcome of the re-expression of E2 and TNF-α treatment in SiHa (human cervical cancer) cells, considering the role of NF-κB, a major regulator of inflammation, proliferation/survival and DNA damage-induced senescence." (PMID 25572145, 2015). "Therefore, this NF-κB/miR-130a/TNF-a/NF-κB feedback signaling pathway may play an important role in the growth regulation of cervical cancer cells." (PMID 24885472, 2014). "In addition, cervix carcinoma cells can be resistant to the cytolytic action of TNF-α or TNF-β and an additional stressor, such as treatment with a protein synthesis inhibitor or radiation, is needed for TNF-induced cytolysis." (PMID 18257926, 2008). "In addition, cervix carcinoma and SiHa cells have been shown to express TNF mRNA." (PMID 18257926, 2008). "Moreover, several cervical carcinoma-derived cell lines are resistant to TNF anti-proliferative effect suggesting that the acquisition of TNF-resistance may constitute an important step in HPV-mediated carcinogenesis." (PMID 18588690, 2008). "The mechanisms for possible promotion of cervix carcinoma growth by TNF-α may include the stimulation of HPV-infected carcinoma cell growth in culture medium depleted from growth factors, induction of HPV-16 E6/E7 expression, and/or stimulation of epithelial tumor cell motility." (PMID 18257926, 2008). "Thus, the effect of TNF-α and histamine on cervical carcinoma cell lines was studied." (PMID 18257926, 2008). "In cervical cancer, persistent HPV infection shifts the balance towards chronic low-grade inflammation where IL-6 and TNF-α predominantly support tumorigenesis." (PMID 41497141, 2026). "Atopobiaceae (CST IV) were enriched in cLSIL, cHSIL, and cervical carcinoma and positively correlated with IL-1α, IL-4, IL-10, IL-12, IL-36γ, IFN-α2, IFN-γ, and TNF-α in cervicovaginal lavages." (PMID 40362199, 2025). "In this study, we investigated the effects of DHC on tumor necrosis factor-α (TNF-α)-induced cell cycle arrest and apoptosis in HeLa human cervical cancer cells." (PMID 40507823, 2025). "inhibited the proliferation and promoted the apoptosis of HeLa cervical cancer cells by activating the MAPK, TNF, and PI3K-Akt signaling pathways." (PMID 39329966, 2024). "UA at 10, 30 and 100 μM concentrations has been shown to decrease PD-L1 levels in HeLa cervical cancer, A549 lung cancer, HCT116 colorectal cancer and liver cancer Hep3B cells, even if TNF stimulated production of PD-L1-α." (PMID 39457512, 2024). "In this study, we found that TNF-α and TGF-β1 in the cell model of advanced cervical cancer upregulated N-cadherin and Vimentin proteins, which contributed to the increased proliferation and invasion of CaSki cells." (PMID 37445768, 2023). "Quercetin influenced several signaling pathways, including TNF, TRAIL and FASL, and induced cell apoptosis in cervical cancer." (PMID 37704909, 2023). "PTX counteracted TNF-α and TGF-β1 induced EMT in cervical cancer cells via NF-κB and TGF-β1/Smad pathways." (PMID 37445768, 2023). "In this study, cervical cancer cells were cultured in Dulbecco's modified Eagle's medium (DMEM) with or without TNF-α for 48 h, and then the corresponding conditional medium (CM-TNF-α or CM) was collected." (PMID 37124061, 2023). "N-cadherin was upregulated when cervical cancer cells were treated with TGF-β, TNF-α, and chemokine CCL20." (PMID 36766756, 2023).
cervical carcinoma (continued). "The level of cytokines such as IL-6, IL-10, IL-8, TNF-α, and VEGF can be co-related with disease progression in ovarian, breast, and cervical carcinoma." (PMID 37746258, 2023). "Consequently, TNFα may be a good therapeutic target against cervical cancer." (PMID 36769377, 2023). "Our experiments demonstrate that EVs from cervical cancer patients after radiotherapy contributed to the M2-like to M1-like phenotype transition (increased expression of CCR7, TNFα and iNOS, and decreased expression of CD163 and IL-10)." (PMID 35062905, 2022). "LMP induced by TNF-alpha has been shown to be dependent on CTSB and the cationic amphiphilic drug resveratrol has been shown to induce LMP in cervical cancer cells that are dependent on autophagy and CTSL." (PMID 33919392, 2021). "Results showed that the expression profiles of cytokines detected in the two cervical cancer cell lines were consistent and IL‐2, IL‐4, IL‐6, IL‐8, IFN‐γ, MCP‐1 and TNF‐α were all expressed." (PMID 31943744, 2020). "The SIRPα knockdown in DCs results in increased cytokine (TNF-α/IL-12/IL-6) secretion, IFN-γ secretion by T lymphocytes, and in vitro/in vivo tumoricidal activity against cervical cancer." (PMID 32411788, 2020). "Since TNF and TRAIL promote OS as part of their mechanism of action, we studied the production of ROS, RNS and hydrogen peroxide (H2O2) in cervical cancer-derived cell lines and in keratinocytes transduced with HPV early genes." (PMID 30625987, 2019). "In this study, we analyzed the effect of TNF and TRAIL on the proliferation and viability of cervical cancer-derived cell lines and primary human keratinocytes (PHK) transduced with E6 and E7 of HPV11 and HPV16 grown in monolayer and organotypic cultures." (PMID 30625987, 2019). "Because TNF-α as an antitumor factor is negatively regulated by Lnc-IL7R, thus, we investigated its correlation in cervical cancer." (PMID 29720427, 2018). "TNF-α decreased and IFN-γ increased in the culture supernatant of monocytes, and the cytomorphology of neem-treated cervical cancer cells showed an increased apoptosis level." (PMID 30563141, 2018). "In turn, TNF-α has been shown to stimulate CK2 activity in Swiss 3T3, L929 and human cervical carcinoma HeLa cells, and IL-1 has been found to activate CK2 in intestinal epithelial cells." (PMID 26732432, 2016). "Tumour necrosis factor-α (TNF-α) has been shown to stimulate CK2 activity in Swiss L929, 3T3 and human cervical carcinoma HeLa cells, and interleukin-1 (IL-1) has been reported to activate CK2 in intestinal epithelial cells." (PMID 26732432, 2016). "The levels of IL-1beta, IL-2, TNF-alpha, and IL-10 were negatively correlated with the percentages of CD4+NKG2D+ T cells in patients with cervical carcinoma." (PMID 26486970, 2015). "HO-1 inhibition in cervical cancer cells HeLa, SiHa, and C-33A induce an increase in IFN-γ and TNF-α production in CD107a + NK-92 cells and restore downmodulation of NKG2D, NKp30, and NKp46 in NK cells." (PMID 25302050, 2014). "Tumor necrosis factor alpha (TNF-alpha), involved in the defense against HPV infection, plays an important role in cervical cancer progression and regression." (PMID 23028877, 2012). "It is previously reported that TNF-α up-regulates MTDH expression at both the mRNA and protein level in the human cervical carcinoma cell line HeLa." (PMID 22768080, 2012). "Instead, no apparent changes in the cell cycle or mitotic regulatory proteins by TNF-α was observed in HPV-18-immortalized keratinocytes and in cervical carcinoma cells, including SiHa and HeLa cell lines." (PMID 18257926, 2008). "A study comprising 91 cervical cancer cases discovered a correlation between low hemoglobin and elevated levels of reactive oxygen species, CRP, IL-1, TNF-α, ß, and IL-6, multivariate analysis revealed that IL-6 was a separate factor influencing hemoglobin levels." (PMID 41142623, 2025).